MMP2 (matrix metallopeptidase 2)
Diseases named in the same sentence as MMP2 in open-access papers (continued):
Sharing a sentence is not in itself a finding about the gene and the disease.
cancer (continued). "Numerous studies have implicated MMP2 and MMP9 as active contributors of malignant progression because they enhance cancer cell migration and invasion." (PMID 34142438, 2021). "This process is critical for cancer-cell invasion, and it includes the proteolytic degradation of the EM by enzymes such as MMP2 and MMP9." (PMID 35366261, 2021). "Meanwhile, GA can exert its potent inhibition on cancer cell invasion and metastasis by downregulation of algogenic substances such as matrix metalloproteinase -2/9 (MMP-2/9) via the anti-inflammatory response." (PMID 34885698, 2021). "Among the MMPs family, MMP2 and MMP9 are involved in the breakdown of extracellular matrix in normal processes, so they are closely associated with the cancer cell migration." (PMID 35059399, 2021). "Further, we observed that marker genes related to cancer aggressiveness—MMP2, β-catenin, and integrin β1—were expressed at higher levels in the g-dECM bioink." (PMID 33816446, 2021). "Cancer tissues exhibited a higher level mRNA expression of MMP-2 and MMP-9 than pericarcinoma tissues, and this difference was statistically significant." (PMID 31882379, 2021). "In this study, the expression of MMP-2 mRNA and protein was found in TAMs together with cancer cells." (PMID 33441903, 2021). "RNA was then screened by PCR using primers specific for miR-365, as well as matrix metalloproteinase (MMP-2) and a downstream cancer stem cell regulator (NKX2.1), and structural and metabolic standards (beta actin, GAPDH)." (PMID 34204617, 2021). "Secondly, our in vivo analysis of MMP2, a critical regulator of cancer cell invasion and metastasis, shows that Orai3 knockdown decreases the expression of MMP2." (PMID 34885048, 2021). "Considering the functional importance of MMP-2 in our model (for CTX to increase cancer cell number at 3 h), we expected that MMP-2 plays a role in the ability of CTX to increase vascular permeability." (PMID 34638621, 2021). "The use of chalcones for the treatment of different cancers has also shown that they can reduce cell migration and invasion by reducing MMP-2 and MMP-9 activity through the downregulation of JNK signaling pathways." (PMID 34205043, 2021). "For example, MMP-2 and -9 cleave laminin and collagen IV, respectively, releasing biologically active fragments influencing essential cancer-related processes as angiogenesis and epithelial-to-mesenchymal transition." (PMID 35010907, 2021). "Combining RT with inhibition of MMP-2 activity impaired cancer cell invasion, reduced VEGF secretion and hindered radiation-induced capillary tube formation in vivo, expanding its role to an important regulator of angiogenesis." (PMID 34055644, 2021). "Fucosterol can induce cancer cell apoptosis by increasing the expression of cleaved caspase 3, caspase 9, and Bax and decreasing the expression of Bcl-2, MMP-2, and MMP-9." (PMID 34336128, 2021). "Resveratrol inhibits the metastasis of cancer cells by down-regulating the expression of MMP-2, 9 by inhibiting the c-Jun N-terminal kinase (JNK) pathway." (PMID 34497528, 2021). "These factors increase eHSP90α binding to MMP2, enhancing MMP2 activation and resulting in cancer cell invasion." (PMID 34722515, 2021). "Our data support the notion that MMP-2 remodels the endothelial BM, making important domains accessible for cancer cells to bind." (PMID 34638621, 2021). "These two cancer cells have known for the elevated MMP-2 and MMP-9 expressions, which is relevant to the aim of the present study." (PMID 34181339, 2021). "Double IHC staining revealed MMP-2 positivity not only in cancer cells involved in lymphatic invasion but also in CD163+ and CD206+ M2 TAMs in all 5 cases." (PMID 33441903, 2021). "Recently, the differential expression of matrix metalloproteinases (MMP) family proteins, especially MMP2 and 9 has been studied in the different ethnic groups of cancer patients." (PMID 33996789, 2021).
cancer (continued). "Although there have been few reports of its expression in TAMs thus far, according to the results of this study, both cancer cells and TAMs express MMP-2 and damage the basement membrane of lymphatic vessels, such as macrophages found in inflammatory diseases." (PMID 33441903, 2021). "In particular, the PI MLN2238 reduces the invasion capability of two OS cell lines, reducing the expression of MMP2/9 proteins, and inducing cancer cells apoptosis, by activating Caspase-3, -8 and -9 in both OS and other different tumors." (PMID 34577623, 2021). "Previous reports on other carcinoma cell lines showed treatment with SFN resulted in down-regulation of matrix metalloproteases, MMP-1 and MMP-2, crucial to cancer cell migration and metastasis." (PMID 34316328, 2021). "Since MMP-2 is highly expressed in cancer cells, we opted to suppress MMP-2 instead of overexpressing it in HCT116 cells to create a less invasive cell." (PMID 34429501, 2021). "Another report showed that downregulation of miR-200 family expression by TGFβ induced MMP-2, -9, and fibronectin 1 production and stimulated cancer cell attachment to human primary mesothelial cells." (PMID 35145899, 2021). "We previously reported that PSCs secreted MMP2 and induced BM destruction in the cancer-stromal microenvironment." (PMID 33858491, 2021). "A class of MMPs are the gelatinases that play a critical role in cancer progression and among which are included MMP-2 and MMP-937." (PMID 33633298, 2021). "Other known targets of miRNAs in cancers include MMP2, MMP9, MMP13, MMP14, and MMP16 and their substrates such as type I, II, and IV collagens." (PMID 33920915, 2021). "These processes involve the role of MMP-9 and MMP-2 by altering the ECM components, which causes the cancer cells to invade the neighboring cells." (PMID 34181339, 2021). "It has been shown that MMP-9 and MMP-2 released from CAFs can stimulate the potential of invasion and migration in carcinoma cells." (PMID 34680267, 2021). "Overactivated NF-κB signaling upregulates MMP9 and MMP2 expression to facilitate migration and invasion of cancer cells." (PMID 32637415, 2020). "Other studies highlighted that TLR-4 increased the rate of lung metastasis in inflamed mice through the upregulation of C–C chemokine receptor type 2 (CCR2) expression and proved that the TLR4/Myd88/NF-κB/MMP2 axis plays a crucial role in cancer metastasis." (PMID 32367494, 2020). "Among MMP members, the pathological significance and prognostic roles of MMP-2 and -9 have been investigated most widely in many types of cancers." (PMID 33333858, 2020). "Many downstream genes of STAT3 have been identified in human cancers, including genes associated with cell cycle (cyclin D1 and cMyc), apoptosis (Bcl2-xL and Mcl-1) and metastasis (MMP1 and MMP2)." (PMID 32161621, 2020). "Matrix metalloprotease protein 2 (MMP2), serving as a cancer metastasis promoting factor, was also down‐regulated in both UGDH‐silencing TOV21G, A2780 and HeyA8 cells." (PMID 32893977, 2020). "In turn, cancer cell-derived signals triggered the expression of metalloproteinases (MMPs) including MMP2, MMP9, and MMP12 in SCs, promoting SCs to dissolve matrix." (PMID 32064233, 2020). "Our other studies indicate that the inhibition of the MMP-2 expression by anti-cancer agent isorhapontigenin (ISO) significantly attenuated both BC invasion in vitro and highly invasive BC formation in vivo." (PMID 31772330, 2020). "The medium levels of TIMP-2 and MMP-2/TIMP-2 complex in serum were higher in healthy women than in cases with a malignant tumor." (PMID 32751899, 2020). "MMP-2 activity and the expression of PCNA, Ki-67 and CD31 which are associated with cancer growth, invasion, and migration, increased after CIH treatment." (PMID 32024881, 2020). "MMP2 belongs to the zinc-dependent metalloproteinase gene family and plays a critical role in cancer metastasis." (PMID 33008449, 2020).
cancer (continued). "Fibronectin 1 (FN1) is a glycoprotein in the ECM, which can mediate the metastasis of various cancers by activating MMP2 and MMP9 expression." (PMID 32943996, 2020). "FAK has also been reported to regulate expression of MMP-2, and its inhibitor reduced MMP-2 and invasion in cancer cells." (PMID 33178272, 2020). "Targeting the FOXO1 activity by ISO treatment resulted in the downregulation of matrix metalloproteinases-2 (MMP-2) and inhibited cancer cell invasion." (PMID 32726968, 2020). "Matrix metalloproteinases (MMP) family such as MMP-9 and MMP-2 can play an important role in cancer proliferation, invasion, and metastasis." (PMID 33027960, 2020). "The cancer metastasis is characterized by the depletion of E-cadherin and upregulation of Snail and metalloproteinases (MMP2 and MMP9)." (PMID 32365503, 2020). "The cancer cell lines with high MMP2 expression (coloured in red) showed more enrichment of H3K27ac at the MMP2 locus, as compared to those with low MMP2 expression (coloured in blue)." (PMID 32499570, 2020). "The findings are consistent with previous reports showing that sinomenine inhibits invasion in various cancer cells through the downregulation of the MMP-2/-9 expression." (PMID 32349289, 2020). "An invasive GBM phenotype is characterized by high ability of cancer cells to degrade and migrate through the ECM, which is associated with the activity of matrix metalloproteinases MMP-2 and MMP-9, responsible for the ECM remodeling." (PMID 32545852, 2020). "CDKN2A (p16), used as a key biomarker for HPV status, exhibited the most extensive hyper-5hmC in HPV(+) tumors, while HPV(−) tumors showed hyper-5hmC in CDH13, TIMP2, MMP2 and other cancer-related genes." (PMID 33203436, 2020). "Studies using several cancer cell lines have strongly suggested the involvement of aberrant epigenetic regulations of MMP-2 in cancer progression." (PMID 33028834, 2020). "Among all the parameters, the highest SE in all stages of cancer was observed for MMP-2 (93.10%, 82.76%; 96.88%; respectively)." (PMID 30820752, 2020). "Melittin/avidin conjugates, which are cleavable by matrix metalloproteinase 2 (MMP2), were designed to directly target the cytotoxic effects of melittin to cancer cells." (PMID 31973181, 2020). "Factors secreted by TAMs, such as TGF-β, VEGF, CCL8, COX-2, MMP9, and MMP2 also contribute to the metastatic properties of cancer cells." (PMID 33352665, 2020). "Matrix metalloproteinases (MMPs) play significant roles in cancer diseases, with MMP-2 and MMP-9 being important types among the various MMPs." (PMID 32967141, 2020). "In contrast, NWXF treatment inhibited the binding activity of Sp1 to the MMP2 promoter, resulting in decreased MMP2 expression, which is crucial for cancer migration and invasion." (PMID 33329003, 2020). "This is the key step in the cancer cell invasion and metastasis, as a lot of flavonoids of MMP-2 and (or) MMP-9 have an inhibitory effect." (PMID 33265939, 2020). "Expression and activity of MMP-2 are correlated with poor prognosis, invasion, and metastasis in many human cancer types." (PMID 33379356, 2020). "Given the significant role of MMP-2 in cancer dissemination, targeting of this molecule, better than FAK, presents a more promising opportunity to block metastasis." (PMID 33321813, 2020). "Their findings indicated significantly higher expression of MMP-2 in malignant tumors in comparison with benign neoplasms." (PMID 32582823, 2020). "Functional blockade with monoclonal antibodies binding to α2, β1, and α2β1 integrin inhibited disaggregation and activation of MMP2/MMP9 in cancer spheroids." (PMID 33026975, 2020). "Among all parameters, the highest SE in all stages of cancer was observed for MMP-2 (in stage I of CC – 93.10%, in stage II of CC – 82.76%, and in stages III and IV of CC – 96.88%)." (PMID 30820752, 2020).
cancer (continued). "Suppression of cancer cells metastasis has been investigated through down‐regulation of Hsp90 expression and/or disruption of the interaction of Hsp90 with MMP‐2/9." (PMID 32180962, 2020). "Many factors, such as TGF-β, activating protein-1 (AP-1) and EGF, interact with the promoter of MMP9 and MMP2 to induce the expression of MMP9 and MMP2 in cancer cells." (PMID 32637415, 2020). "We have also shown here that suramin inhibits eATP-mediated COX-2 and MMP-2 synthesis and prevents cancer cell migration and invasion." (PMID 33584298, 2020). "We indicated that the SE of the tested cytokines in the total cancer group was the highest for MMP-2 (92.05%)." (PMID 30820752, 2020). "As a member of the MMP family, MMP2 plays a central role in malignant tumors and predicts a poor prognosis." (PMID 33251331, 2020). "Invasive abilities of cancer cells are related to migration and many other factors, including expressions of MMP-2, MMP-9, Rac1, Rho A, and SOD2." (PMID 31772330, 2020). "Consistently, our combined analyses of the RNA-Seq and H3K27ac ChIP-seq data for MMP2 showed varied degrees of MMP2 expression among several types of cancer cell lines, despite the equally high expression of BRD4 among them." (PMID 32499570, 2020). "MMP2 is an identified molecule closely related to invasion, angiogenesis and metastasis in many cancers including GC." (PMID 32576271, 2020). "Evidence supporting our findings regarding mobilized cells against gravity are cancer cells that polymerize actin to form protrusions and activate their migration pathways as MMP-2, MMP-9, under microgravity environments." (PMID 33158020, 2020). "Alternatively, MMP-2 activity has been considered pre-clinically for detection of cancer using an MMP-2-responsive nanoprobe system, due to the overexpression of this enzyme in tumors." (PMID 32042347, 2020). "Herein, we systematically explored the dysregulation of MMPs in human cancers and demonstrated that MMP2/9 highly correlates with TILs." (PMID 32988398, 2020). "Increased expression of suppressive alarmins, e.g., matrix metalloproteinase-2 (MMP-2) is also detected in cancer cells." (PMID 32645977, 2020). "Propofol increases miRNA-218 and miRNA-451 expression, whereas it reduces MMP-2 protein expression and cancer cell proliferation in vitro." (PMID 32863874, 2020). "MMP2 expression was significantly higher in epithelial cells of colon mucosa 10 cm and 20 cm away from the cancer, compared with healthy mucosa (p = 0.037 and p = 0.034)." (PMID 32286443, 2020). "MMP2 expression was significantly higher in lamina propria of colon mucosa 10 cm away from the cancer, compared with healthy controls (p < 0.0001)." (PMID 32286443, 2020). "A number of studies reported that MMP families, including MMP-2, are enriched at invadopodia and required for cancer-cell invasion." (PMID 32858793, 2020). "Rac1-regulated NF-κB transcriptional activity is required for MMP-2/-9-driven invasion of cancer cells." (PMID 32823607, 2020). "Currently, a particular group of matrix metalloproteinases (MMPs) named gelatinases (MMP-2 and MMP-9) is greatly associated to cancer invasion through degradation of the cellular matrix, and the consequent release of cancer cells via proteolysis." (PMID 33308217, 2020). "The NOB suppresses the motility and invasion of cancer cells via the downregulation of MMP-2 and MMP-9." (PMID 32380783, 2020). "PI3K–Akt signaling is reported to be involved in cancer cell invasion by modulating NF-κB-mediated MMP-2 expression through the control of Rac1 activity." (PMID 32033487, 2020). "It has been reported that MMP2 and MMP9 cause the proteolysis of ECM components and induction of cancer cell invasion." (PMID 32266797, 2020). "MMP-2 was the first endopeptidase recognized to degrade collagens and to be related to the invasive and metastatic potential of cancer cells." (PMID 33308217, 2020).
cancer (continued). "In mesenchymal cells, MMP-2 was shown to cleave fibronectin into smaller fragments and thereby increase the chances of these circulating cancer cells to attach to the secondary sites." (PMID 32751717, 2020). "An important enzyme required for the invasiveness of cancer cells is gelatinase or matrix metalloproteinases, of which matrix metalloproteinase 2 (MMP-2) has been widely reported in various cell culture studies." (PMID 33584298, 2020). "The inhibitory effect of EGCG upon P-gp increases gallic acid concentration in cancer cells leading to inhibition of matrix metaloproteinases (MMP-2, MMP-9)." (PMID 31936346, 2020). "Most interestingly, the overexpression of cofilin in multiple invasive cancer cell lines enhances the cellular invasiveness and increases the enzymatic activity of MMP-2." (PMID 33043017, 2020). "The outgrowth of cancer cells after a dormancy period necessitates the MMP-2-driven breakdown of fibronectin." (PMID 33043017, 2020). "While in our study, the activities of pristimerin to reduce the cellular cytoskeleton of vimentin and F-actin, cellular adhesion of integrin β1, as well as cellular invasion of MMP2, exerted the multiple ways of anti-cancer potential." (PMID 33033518, 2020). "Degradation of extracellular matrix (ECM) by matrix metalloproteases (MMPs), particularly MMP2/9, is required for cancer cell metastasis." (PMID 33371405, 2020). "PTTG1 has been shown to transcriptionally activate expression of a wide range of target genes, including c-Myc, FGF-2, cyclin D3, p21, and MMP-2, most of which are critically involved in cancer proliferation and metastasis." (PMID 33250768, 2020). "CD147 been reported to enhance the invasive potential of cancer cells in part due to overexpression of MMP-2 and MMP-9 (Metalloproteinase 2 and 9)." (PMID 31973205, 2020). "Zn level was not considered in previous studies investigating association of MMP-1, MMP-2, MMP-7, MMP-13 and MT2A polymorphism with cancer risk." (PMID 32765800, 2020). "A large number of studies confirmed that the abnormally high expression of MMP-2/9 is closely related to the variety of metastasis and poor prognosis of cancer." (PMID 32184893, 2020). "MMP2 and MMP9 are closely associated with cancer metastasis due to their strong proteolytic activity of the ECM (extracellular matrix)." (PMID 32650804, 2020). "MMP-2 is over-expressed in cancer tissues, and its increased expression correlates with advanced cancer stage and poor prognosis." (PMID 33027062, 2020). "Tissue inhibitor of metalloproteinase-2 (TIMP-2) is an endogenous inhibitor of matrix metalloproteinase-2 (MMP-2), an important enzyme in the regulation of cancer cell proliferation and metastasis." (PMID 33027062, 2020). "Given the significant involvement of MMPs in cancer cell migration and invasion, we checked the protein expression of MMP-2 in FaDu and HSC-3 cells after the treatment with various concentrations (0, 10, 20, and 40 μM) of luteolin-7-O-glucoside for 24 h." (PMID 32224968, 2020). "Among the 24 members of the MMP family, previous researches have focused on the tumourigenic role of MMP9 and MMP2 for many malignant carcinomas." (PMID 31937294, 2020). "MMP is a type of extracellular proteolytic enzyme, which can degrade basal membrane and promote invasion and migration of malignant tumors, of which MMP-2 and MMP-9 are two primary enzymes to degrade type IV collagen." (PMID 31101062, 2019). "The results showed interaction between HE4/ANXA2 and MMP2 was common in various malignant tumor cells including CaoV3, ES-2, OVCAR-3, Ishikawa, A549, HGC-27, SW480, HepG2, Hela, HT29 and HEK293 cell lines." (PMID 31210752, 2019). "As a transcription factor, FOXM1 has many target genes including KIF20A, CENPF, CCNB1, MYC, NIMA-related kinase 2, MMP2, MMP9, and S-phase kinase-associated protein 2 that are implicated in cancer initiation, progression, or drug resistance." (PMID 31072351, 2019).